TGFB1 (transforming growth factor beta 1)
Diseases named in the same sentence as TGFB1 in open-access papers (continued):
Sharing a sentence is not in itself a finding about the gene and the disease.
pulmonary fibrosis (continued). "However, the lung tissue relative mRNA expression of the chloride (cystic fibrosis transmembrane conductance regulator) and sodium (Scnnγ, Scnnβ) channels were significantly decreased in TGFβ1 TG mice with lung fibrosis compared to WT and TGFβ1 TG mice without lung fibrosis." (PMID 32210242, 2020). "Normal lung fibroblasts (NLF) and fibroblasts derived from lungs of individuals with idiopathic pulmonary fibrosis (IPF) were cultured in the presence of TGFβ1, with or without addition of mEVs or fibroblast-derived EVs (fEVs) (10 μg)." (PMID 29273797, 2017).
liver fibrosis (2,337 papers, 2004 to 2026). "The evaluation involved measuring serum levels of key biomarkers associated with liver fibrosis, including fibronectin (FN), hyaluronic acid (HA), and transforming growth factor beta-1 (TGF-β1)." (PMID 39789197, 2025). "Platelets also attenuate liver fibrosis by degrading ECM, although platelet-derived TGFβ1 has been shown to be pathogenic in cardiac or liver fibrosis." (PMID 37643008, 2023). "CTGF silencing in liver fibrosis rodent models has shown to cause a decrease in the transcription of TGFB1, ACTA2 and COL1A1." (PMID 36672237, 2023). "In the murine NASH model, DX5+ (anti-CD49b antibody) NKp46+NK cells can prevent liver fibrosis progression by suppressing M2-like macrophage polarization and the expression of profibrotic genes (e.g., Tgfb1 encoding transforming growth factor-beta 1)." (PMID 37239062, 2023). "The mRNAs levels of hepatic fibrosis-associated markers, such as Col1α2, Col3α1, and Tgfβ1 were significantly enhanced in Agk-/- hepatocytes." (PMID 35547757, 2022). "Increased levels of TGFβ1 have been linked to EMT in biliary epithelial cells before the progression of liver disease to hepatic fibrosis." (PMID 33525359, 2021). "To verify the clinical associations among splenectomy, LIGHT, and TGFβ-1, we used a ConA-induced mouse liver fibrosis model." (PMID 33654222, 2021). "TGFβ1 signaling is important in activating hepatic stellate cells and implicated in hepatic fibrosis." (PMID 32373112, 2020). "IPA identified Hepatic fibrosis/hepatic stellate cell activation as the main canonical pathway in TGFβ1-treated qVICs, involving genes typically associated with aVICs in diseased tissue." (PMID 31415646, 2019). "In conclusion, we have demonstrated that MICA rs2596542 is associated with liver fibrosis progression, likely mediated and amplified in part through TGFβ-1 dependent mechanisms." (PMID 30723271, 2019). "Previous study has demonstrated that the development of hepatic fibrosis, a wound-healing response to liver injury, is associated with the pathway mediated by overexpression of cytokine transforming growth factor-beta 1 (TGFB1)." (PMID 31065454, 2019). "CoQ10 treatment in a model of hepatic fibrosis ameliorates liver damage via suppression of Tgfb1 and upregulation of Nrf-ARE-associated genes." (PMID 26718412, 2016). "This sub-cluster is highly enriched in genes related to liver fibrosis, including 11 collagen genes and genes encoding TGFB1, matrix metalloproteinases, tissue inhibitors of metalloproteinases, and lysyl oxidase like proteins." (PMID 27007663, 2016). "In this study overexpression of the gene encoding TGFβ1 in mice was shown to initiate severe liver fibrosis as evidenced by histology." (PMID 17883846, 2007). "Thus, SMSr deficiency or PE administration effectively prevented TGFβ1-mediated overexpression of liver fibrosis genes." (PMID 37586586, 2023). "Taken together, the mechanisms underlying the effects of SREBP1c on HSC activation and liver fibrosis were involved in its influences on TGFβ1 level, the receptors for TGFβ1 and PDGFβ and their downstream signalling, and the molecules for epigenetic regulation of genes." (PMID 32678475, 2020). "Previous researches revealed that Nogo-b could cause hepatic fibrosis through TGFβ1/Smad2 signaling pathway." (PMID 29050340, 2017). "For example, the combination of angiotensinogen (ATG) gene variant c.1-44 and transforming growth factor beta (TGFβ1) p.R25P is associated with advanced hepatic fibrosis in obese patients with non alcoholic fatty liver disease but not in patients with other chronic liver diseases." (PMID 20170533, 2010). "In addition, macrophage-specific Pparγ deficiency showed significantly increased expression of liver fibrosis-related genes, such as transforming growth factor-beta 1 (TGF-β1), actin alpha 2, collagen type I alpha 1 (COL1A1), and tissue inhibitor of metalloproteinase (TIMP)-1, in MASH liver." (PMID 39200340, 2024).
liver fibrosis (continued). "Interestingly, even if hepatic stellate cells are widely considered the main matrix-producing cells driving liver fibrosis, recent studies have also described a TGFβ1/SMAD-dependent EMT of hepatocytes associated with the processes of hepatic fibrosis, a key condition for liver metastatic priming." (PMID 37072829, 2023). "The results showed that PE supplementation in LX-2 cells significantly reduced TGFβ1-induced production of fibrosis proteins (i.e., collagen 1α1, platelet-derived growth factor receptor (PDGFR)α, and PDGFRβ), suggesting that PE supplementation could rescue liver fibrosis caused by TGFβ1 stimulation." (PMID 37586586, 2023). "TGFβ1 is a ubiquitously expressed master switch that induces the fibrotic program in various cell types including cardiac fibroblasts and has been implicated in multiple fibroproliferative diseases including: glomerulosclerosis, ulcerative colitis, hepatic fibrosis, glaucoma, and scleroderma." (PMID 23936252, 2013). "In contrast, the expression of liver fibrosis‐related genes (Tgfb1, Col1a1) was significantly increased in the GAN group." (PMID 41559934, 2026). "In mice infected with S. japonicum, treatment with recombinant KLB protein or AAV8-KLB increased the LSEC population, mitigated EMT in both LSEC and liver tissues, ameliorated hepatic fibrosis, and inhibited TGFβ1 pathway activation." (PMID 42154778, 2026). "It is widely acknowledged that the TGFβ1/SMAD3 pathway plays a key role in excessive ROS generation in liver fibrosis, and TGFβ1 can regulate NOX4/ROS pathway through SMAD3 signaling." (PMID 40060764, 2025). "Experimental evidence from hepatocyte-specific Lgals3bp-knockin mice revealed exacerbated hepatic fibrosis accompanied by elevated Tgfb1 levels." (PMID 41209003, 2025). "Our previous study found that NiONPs induced liver fibrosis through activation of transforming growth factor beta 1 (TGF-β1)/Smad, JNK/c-Jun signaling pathways." (PMID 40278581, 2025). "Conversely, forced expression of hepatocyte Serpina3k or SERPINA3 alleviated liver fibrosis by reducing HSC activity through protease-activated receptor 2 (Par2)-mediated TGFβ1 signaling." (PMID 40744994, 2025). "They found that infection with P. gingivalis exacerbated liver fibrosis by activating hepatic stellate cells (HSCs) to produce transforming growth factor-beta 1 (TGF-β1) and galectin-3 (Gal-3) from both HSCs and hepatocytes." (PMID 40564062, 2025). "On the other hand, Cyp4a14 gene overexpression reduced liver fibrosis markers such as Tgfb1 and Acta2 in a model of cholestatic liver fibrosis." (PMID 41180305, 2025). "Overall, our study demonstrates that GSH can improve the engraftment efficiency of ADSCs in liver fibrosis by inhibiting the TGFβ1/SMAD3/NOX4 signaling pathway." (PMID 40060764, 2025). "In CCl4- and TAA-induced liver fibrosis models, the administration of TGFβ1-preconditioned exosomes significantly reduced liver fibrosis." (PMID 40852596, 2025). "It has been reported that intraperitoneal and oral administration of olive oil significantly reduced the levels of MDA and TGFβ1 in liver tissue in mice with carbon tetrachloride (CCl4)-induced liver fibrosis." (PMID 40233022, 2025). "Collagen proportionate area (CPA), hydroxyproline quantification, and assessment of fibrogenic gene expression (Acta2, Col1a, Tgfb1, and Timp1) showed a minor effect of Prdx2 KO on liver fibrosis." (PMID 40932790, 2025). "In the study investigating the effect of Tyr, one of the phenolics of EO, on the nonalcoholic steatohepatitis model, steatosis and hepatic fibrosis and increased TGFβ1 gene expression were observed." (PMID 40233022, 2025). "It has been found that insulin-like growth factor binding protein-related protein 1 (IGFBPrP1) and transforming growth factor beta 1 (TGFβ1) regulates each other and jointly increase the onset and progression of liver fibrosis." (PMID 40110044, 2025).
liver fibrosis (continued). "Treatment with EA also ameliorated liver fibrosis via inhibition of transforming growth factor-beta 1/suppressor of mothers against decapentaplegic (TGF-β1/Smad) pathway and alpha-smooth muscle actin (α-SMA)." (PMID 38542468, 2024). "A pivotal process in the development of hepatic fibrosis is the TGFβ1-dependent activation of hepatic stellate cells whose plasticity is now widely recognized." (PMID 39074160, 2024). "Col1A1, Timp1, and Tgfβ1, which are commonly regarded as fibrosis markers, were upregulated in liver fibrosis." (PMID 38372748, 2024). "TGFB1 was involved in four upregulated signaling pathways including hepatic fibrosis, HMGB1, macrophage classical activation, and wound healing." (PMID 39660530, 2024). "Treatment with α4β7 mAb reduced hepatic fibrosis reflected by decreased collagen deposition in the liver and significant reduction in the transcript levels of Acta2, Col1a1, Col1a2, Tgfb1 and Timp1." (PMID 38727292, 2024). "For instance, EVs derived from human umbilical cord mesenchymal stem cells (Huc-MSCs) have been employed to treat liver fibrosis by reducing transforming growth factor-beta 1 (TGF-β1) expression and inhibiting liver EMT in vivo." (PMID 38675228, 2024). "The level of GPR81 was determined in mice with carbon tetrachloride (CCl4)-induced liver fibrosis and in transforming growth factor beta 1 (TGF-β1)-activated hepatic stellate cells (HSCs) LX-2." (PMID 38982366, 2024). "Further studies are required to explore the specific mechanisms through which EgE2D2 and EgE2N promote liver fibrosis in TGFβ1-induced LX-2 cells." (PMID 38643149, 2024). "The observed imeglimin-mediated attenuation of hepatic fibrosis coincided with decreased hepatic expression levels of genes related to fibrogenesis, including Timp1, Ctgf, and Tgfb1." (PMID 39594556, 2024). "A number of differential canonical pathways (e.g., LXR/RXR activation pathway, glycolysis I gluconeogenesis I, and hepatic fibrosis) and potential upstream regulators (e.g., TGFB1, THBS2, etc.)were also identified." (PMID 39660530, 2024). "HCV infection can promote hepatic fibrosis through a complex molecular mechanism involving the upregulation of both transforming growth factor beta 1 (TGF-β1) and microRNA-192 (miR-192)." (PMID 39772172, 2024). "In liver fibrosis treatment research, when exposed to TGFβ1, SIRT1 activation substantially decreased EZH2 acetylation levels." (PMID 37985432, 2024). "Morin by acting on Hippo/Yap and TGFβ1/Smad pathways, ameliorated experimental liver fibrosis through prevented HSC activation." (PMID 39359922, 2024). "Liver fibrosis in NAFLD is caused by liver inflammation, and major markers of fibrosis are Col1a1, Col3a1, and Tgfβ1." (PMID 37894124, 2023). "We have previously demonstrated that in cirrhotic rats MitoQ decreases the expression of Col1A1 and TGFβ-1 and improves liver fibrosis." (PMID 37107346, 2023). "Specifically, Sct stimulates DR and liver fibrosis (by a paracrine loop) in cholestatic models by enhanced biliary secretion of TGFβ1." (PMID 36624475, 2023). "An anti-transforming growth factor-beta-1 (TGF-β1) aptamer-based sensor has been designed for the detection of liver fibrosis through TGF-β1 monitoring." (PMID 37374056, 2023). "Knockdown of lncRNA-Gm9866 inhibited the apoptosis of HCs, the expression of pro-fibrogenic genes, TGFβ1 induced fibrosis and the occurrence of carbon tetrachloride (CCl4)-induced liver fibrosis, and promoted the proliferation and migration of HCs." (PMID 37919785, 2023). "To elucidate the underlying mechanism by which SGE inhibits HSC activation and liver fibrosis, we examined its effect on TGFβ1 signaling." (PMID 37686772, 2023). "Gene expression of Col1a1, TGFβ-1, TIMP-1, MMP-2, and MMP-9, which are associated with liver fibrosis, was significantly higher in MCDHFD mice than in control animals." (PMID 37107346, 2023).
liver fibrosis (continued). "TNF-α directly increases the expression of mast cell proteinase 1, Tgfb1, and tissue inhibitor of metalloproteinase 1 in hepatocytes, participating in hepatic lipid metabolism, inflammation, and liver fibrosis processes." (PMID 38145041, 2023). "In contrast, downregulation of Sct/SR signaling reduces DR/biliary senescence, liver angiogenesis and liver fibrosis by downregulation of TGFβ1." (PMID 36624475, 2023). "Glucosylceramide stimulates transforming growth factor beta 1 (TGFβ1) activation, which mediates liver fibrosis." (PMID 37686134, 2023). "Several studies have shown that inhibition of Sct-dependent signaling in BDL and Mdr2−/− mice (by genetic knockout or pharmacological inhibition of SR) reduces biliary damage/DR and liver fibrosis by inhibiting TGFβ1 signaling." (PMID 36624475, 2023). "These anti-fibrotic activity results of curcumin and taurine are in concurrent with other studies on hepatic toxicity animal models induced liver fibrosis were treated with curcumin and taurine showed downregulated expression of TGFβ1." (PMID 37214337, 2023). "We found that Microfibril Associated Protein 2 (MFAP2) was elevated in carbon tetrachloride (CCl4)‐induced liver fibrosis and Transforming Growth Factor‐Beta 1 (TGF‐β1)‐activated HSCs." (PMID 37635348, 2023). "In this study, a CCl4-induced rat liver fibrosis model and transforming growth factor-beta 1 (TGF-β1)-treated HSC lines (LX-2 and HSC-T6) were used to detect miR-192 and Rictor levels in vivo and in vitro." (PMID 38152335, 2023). "On mouse hepatic fibrosis brought on by carbon tetrachloride as well as on LX-2 cells (human immortalized HSCs) triggered by transforming growth factor beta 1 (TGF-β1), HD-16 demonstrated an antifibrotic effect both in-vivo and in-vitro." (PMID 37123086, 2023). "A previous study showed that lncRNA-NEAT1 sponged miR-139-5p and promoted HSC activation to regulate liver fibrosis by targeting the β-catenin/SOX9/TGFβ1 pathway." (PMID 37919785, 2023). "The NS3TP1 expression level dramatically decreased in TGFβ1-stimulated LX-2 cells and CCl4-induced fibrotic disease models, suggesting some association between NS3TP1 and liver fibrosis." (PMID 36983568, 2023). "Alcoholic liver disease (ALD) and other forms of chronic hepatotoxic injury can lead to transforming growth factor β1 (TGFβ1)-induced hepatic fibrosis and compromised liver function, underscoring the need to develop novel treatments for these conditions." (PMID 37400491, 2023). "AT1R antagonists have also been shown to decrease AST levels and inhibit hepatic stellate cell activation, oxidative stress, transforming growth factor beta 1 expression, and hepatic fibrosis." (PMID 37173649, 2023). "It is known that only a small portion of liver fibrosis can result in tumors and TGFβ1 is one of the factors promoting this transformation." (PMID 37586586, 2023). "TGFβ1 is also considered as the key cytokine that drives liver fibrosis in patients with chronic liver disease." (PMID 36864321, 2023). "TGFβ1, a STAT3 target gene, promotes liver fibrosis by increasing the expression of TGF-β1 in a liver fibrosis mouse model and a rapid early STAT3 activation was observed in HSCs and fibroblasts, but not in normal hepatocytes." (PMID 37978263, 2023). "Further investigation into the mechanisms by which SREBP1c regulates HSCs and liver fibrosis demonstrated that overexpression of SREBP1c inhibited liver fibrosis in mice by reducing the levels of TGFβ1 and signaling via SMAD3 and Akt1/2/3." (PMID 38137501, 2023). "Activated HSCs produce and deposit type I and III collagen and fibronectin, and release TGFβ1, a potent fibrotic cytokine, leading to hepatic fibrosis." (PMID 35138513, 2022). "And it inhibited the activation of HSCs by regulating TGFβ1/NDRG2/MAPK signaling axis in CCl4-induced liver fibrosis Our study newly found that NLPC0393 inhibited the differentiation of WB-F344 cells into cholangiocytes in a Gli1-dependent manner." (PMID 36483737, 2022).